XPO1 (exportin 1)
Diseases named in the same sentence as XPO1 in open-access papers (continued):
Sharing a sentence is not in itself a finding about the gene and the disease.
cancer (continued). "Over more than a decade, there has been substantial progress in targeting nuclear export in cancer using selective XPO1 inhibitors." (PMID 36722323, 2023). "Pharmacological inhibition of XPO1 leads to blockade of protein synthesis, nuclear retention of tumour suppressor proteins and apoptosis of cancer cells." (PMID 37528310, 2023). "As a result of the pro-survival and proliferative properties of XPO1, it has a critical role in the maintenance of cancer cell survival and is frequently overexpressed in cancer." (PMID 37528310, 2023). "We then tested in silico the possible co-expression of XPO1 (gene coding for CRM1) with 135 cancer-related genes included in the CGA TARGET database of the Broad Institute in various types of solid tumours and AML." (PMID 37046649, 2023). "For example, the nuclear transport receptor XPO1 is frequently overexpressed in cancers, leading to mis-localisation and inactivation of tumour suppressor proteins." (PMID 36648336, 2023). "Cancer cells therefore use XPO1 to excessively export IkB to the cytoplasm and disrupt homeostasis, increasing its degradation and resulting in excessive NFkB signaling." (PMID 36671496, 2023). "XPO1 functions as an exporter of a wide range of cargo molecules that aid in the growth and progression of cancer." (PMID 36671496, 2023). "XPO1 is a major nuclear exporter of many tumor suppressor and chemotherapeutic targets, and overexpression of XPO1 has been shown to be relative to poor prognosis or resistance to chemotherapy in various cancers." (PMID 37370118, 2023). "Pathway analysis revealed that selinexor-treated CF365 tumors had upregulation of the β-catenin degradation pathway, modulated WNT signaling and androgen receptor signaling, which is in line with the known effects of XPO1 inhibition in cancer cells." (PMID 36059685, 2022). "XPO1 mediates the nuclear export of multiple tumor suppressor proteins (TSPs), and its inhibition causes TSP nuclear retention leading to decreased cancer cell proliferation and cancer cell apoptosis, while sparing healthy tissue." (PMID 36059685, 2022). "As cancer cells overexpress XPO1, and many of its cargos include tumor suppressor proteins and complexes bound to oncogene mRNAs, XPO1 inhibition can suppress oncogene translation and restore tumor suppressor protein activity in different cancer types." (PMID 36059685, 2022). "TET1 and TET2 activities are also downregulated in several types of cancer by XPO1-mediated nuclear exportation, which can be restored by the XPO1 inhibitor leptomycin B (LMB)." (PMID 36203205, 2022). "It has been well established that KPT330 exerts its anti-cancer activity by inhibiting nuclear transporter protein exportin-1 (XPO1), also known as CRM150." (PMID 35301428, 2022). "The results showed that XPO1 mRNA expression was significantly increased in GBC tissues compared with that in corresponding non-cancer tissues assessed by Student's t test." (PMID 36180918, 2022). "Our results demonstrate that the combinations of XPO1 inhibitor with KRAS G12C inhibitors can effectively inhibit the proliferation of KRAS G12C–mutant cancer cells in 2D and 3D cultures." (PMID 35573474, 2022). "This compound and its analogs are known as selective inhibitors of nuclear export (SINEs), which are developed to target the nuclear transporter protein XPO1 for anti-cancer treatment." (PMID 35301428, 2022). "KPT-8602 is a second-generation inhibitor of XPO1, demonstrating the lowest level of side effects, and is currently in clinical trials for the treatment of cancers." (PMID 35721113, 2022). "Our previous studies and those of other researchers indicated that XPO1 inhibitors exerted its anticancer activities by inducing apoptosis in cancer cells." (PMID 36180918, 2022). "SXR is an anti-cancer drug that acts by inhibition of nuclear exportin-1 (XPO1), which inhibits transport of nuclear proteins from the nucleus to the cytoplasm, leading to the induction of cell-cycle arrest and apoptosis." (PMID 35559257, 2022).
cancer (continued). "In conclusion, we have shown that the nuclear transport protein XPO1 inhibitor can enhance the anticancer activity of KRAS G12C inhibitors in preclinical cancer models." (PMID 35573474, 2022). "Increased expression of several potentially targetable genes was found at late disease stages, including cancer-testis antigens, XPO1 and ABC transporters." (PMID 35643867, 2022). "XPO1 induces accumulation of nuclear proteins within the nucleus of cancer cells with increasing expression of tumor suppressor genes." (PMID 35559257, 2022). "Since TSPs and many other regulatory proteins only function in the nuclear compartment, resistance to PIs often occurs in the setting of elevated levels of XPO1—mediating the rapid nuclear export and functional inactivation of these key anti-cancer proteins." (PMID 34802051, 2022). "Further, the identification of recurrent missense mutations (XPO1E571K,D724, andR749) has exposed more mechanistic clues to the role of XPO1 in different cancers." (PMID 35091658, 2022). "XPO1 inhibition has evolved as a novel target in cancer therapeutics with potential utility across different cancer types." (PMID 35091658, 2022). "In summary, XPO1 inhibition primes cancer cells for NK cell mediated cytotoxicity via HLA-E downregulation, and SINEs in combination with NK cell directed therapies has potential to promote anti-tumour responses in patients." (PMID 36560403, 2022). "Studies have found that XPO1 protein is elevated in many cancers, such as osteosarcoma, pancreatic cancer and ovarian cancer 5-7." (PMID 34975332, 2022). "The circXPO1 was derived from a well-established cancer therapeutic target, XPO1, which was highly expressed in LUAD tissues compared with paired controls." (PMID 36212131, 2022). "It has been proved that XPO1 inhibition locks cargo proteins, leading to selective apoptosis of cancer cells, whereas normal cells undergo transient cell cycle arrest." (PMID 34575598, 2021). "We will further explore the current state of pre-clinical and clinical development of XPO1 inhibitors in childhood cancers." (PMID 34944778, 2021). "One family of novel compounds, termed SINE, inhibit the major nuclear export protein Exportin 1 (XPO1), which is frequently overexpressed in cancer." (PMID 33438820, 2021). "Selinexor is an exportin‐1 (XPO1) inhibitor, and the CRISPR‐Cas9 system was used to show that resistance of cancer cells to this drug was because of mutations at the cysteine‐528 in the XPO1 gene." (PMID 34188916, 2021). "Targeted inhibition of XPO1 by the selective inhibitor selinexor leads to cancer cell death through accumulation of tumor suppressor proteins in the nucleus, dysregulation of growth regulatory proteins and blockade of oncogene protein translation." (PMID 34926302, 2021). "Recently, small molecule inhibitors of XPO1 termed SINEs have gained increasing attention as anti-cancer molecules, with specific emphasis toward hematologic malignancies." (PMID 33451349, 2021). "SINE compounds bind to XPO1 long enough to kill cancer cells, but their reversible nature allows them to be released in time to spare normal cells." (PMID 34584169, 2021). "CircXPO1 (circBase ID: hsa_circ_0001016, alias: hsa_circ_001767) is a novel circRNA that is derived from back-spliced exportin 1 (XPO1), a well-known cancer therapeutic target." (PMID 34386427, 2021). "In this review, we will focus on the differential biology of childhood and adult cancers as it relates to XPO1 and key cargo proteins." (PMID 34944778, 2021). "The drug is a first-class exportin-1 (XPO1) inhibitor that brings apoptosis in cancer cells by blocking nucleocytoplasmic transport of tumor suppressor proteins." (PMID 33995121, 2021).
cancer (continued). "On the other hand, selective and reversible disruption of XPO1-mediated nuclear transport is sufficient to interfere with cancer progression and viral replication." (PMID 34584169, 2021). "The chalcone derivatives were evaluated in antiproliferative assays against a panel of cancer cell lines and as XPO1 inhibitors, and a good correlation was observed with the results obtained in both assays." (PMID 34832913, 2021). "Selinexor is a first-in-class, oral, small molecule Exportin-1 inhibitor that is being developed for the treatment of a variety of cancers, including AML." (PMID 34889237, 2021). "Across nearly all cancers, including those affecting children, adolescents, and young adults, XPO1 is expressed, and higher expression has been correlated with inferior outcome." (PMID 34944778, 2021). "Of note, XPO1 overexpression correlates with poor clinical outcome in many kind of cancers (ovarian, pancreatic, osteosarcoma, glioma, and cervical cancer." (PMID 34575598, 2021). "Upregulation of XPO1 is common in human cancers and results in abnormal tumor suppressor protein export with imbalance favoring proto-oncogene activity." (PMID 34926302, 2021). "Recently developed XPO1 inhibitors showed success in slowing tumorigenesis in a variety of cancers and the selective inhibitor of nuclear export (SINE), Selinexor (KPT-330, Karyopharm Therapeutics), was approved for relapsed multiple myelomas in 2020." (PMID 35047088, 2021). "The role of selinexor and second generation XPO1 inhibitors in other cancer types and in combinations is still being examined." (PMID 34829820, 2021). "While XPO1 and its role in regulating mitosis is important, in the context of cancer targeting and treatment; the focus has been on its role as a nuclear export protein and the disruption of downstream signaling pathways." (PMID 34944778, 2021). "Our data identifies that the selective XPO1 inhibitor selinexor disrupts the inhibitory NKG2A:HLA-E axis to activate NK cells against cancer." (PMID 34926302, 2021). "XPO1 was found to be up-regulated in several cancer types and was demonstrated to dysregulate intracellular localization of tumor suppressors and oncogenes, modulate autophagy, and contribute to tumor growth and progression." (PMID 32971786, 2020). "XPO1 is one of the key mediators of nuclear export, which is a crucial step in intracellular signaling, and it is utilized by cancer cells to stimulate cell proliferation and evade apoptosis." (PMID 32971786, 2020). "The availability of biomarkers predictive of therapeutic responses and toxicity will help identify the target patient population and exploit the full potential of XPO1 inhibitors in cancer treatment." (PMID 32487143, 2020). "XPO1 overexpression is a common feature among many human cancer types, including pancreatic, ovarian, glioma, lung, gastric, prostate, and colorectal cancers, and is associated with poor prognosis." (PMID 32487143, 2020). "There is a growing interest in targeting XPO1 in cancer treatment, and various SINEs have been developed, including Selinexor, and are still under development." (PMID 33007990, 2020). "Due to frequent deregulation in cancers, XPO1 has been identified as a therapeutic target in many tumor types." (PMID 32487143, 2020). "Here, we characterized a novel circRNA, circXPO1, in LUAD, which is derived from a well-established cancer therapeutic target, XPO1." (PMID 33268793, 2020). "Specific XPO1 inhibitors have been extensively tested and demonstrated efficacy in a broad range of cancer types in preclinical studies." (PMID 32487143, 2020). "Expression levels of XPO1 are elevated in cancer cells, which leads to excessive nuclear export and dysfunction of tumor suppressor proteins." (PMID 32612949, 2020).
cancer (continued). "In the present study, we apply a recently described nuclear export reporter termed SRVB/A to map new sequence motifs with nuclear export activity in “XPO1/CRM1-cancer exportome” proteins, and to gain further insight into CRM1-mediated NES export." (PMID 32882917, 2020). "In this light, extensive genetic and preclinical studies and well-designed clinical trials are the prerequisite to exploiting the full potential of XPO1 inhibitors in cancer treatment." (PMID 32487143, 2020). "XPO1 overexpression also correlates with poor prognosis and radiotherapy resistance in some cancers." (PMID 32612949, 2020). "To determine how this assay compares to the well-established Rev(1.4)-GFP assay in this task, we decided to use both systems in an effort to map novel NESs in proteins that conform the “XPO1/CRM1-cancer exportome”." (PMID 32882917, 2020). "First, XPO1 is frequently overexpressed in human cancers, while XPO1 suppression has been shown to reduce the protein levels of driver oncogenes, such as MYC and EGFR, in multiple cancer types." (PMID 32487143, 2020). "Our data were consistent with other investigators’ reports, showing a higher expression of XPO1 in pancreatic and other cancers." (PMID 31382411, 2019). "We defined two classes of primary cancer samples that were based upon XPO1 expression in tumors when compared with mean expression in normal pancreatic samples: the “XPO1-high” class (N = 298; 52%) and the “XPO-low” class (N = 275, 48%)." (PMID 31052304, 2019). "Identification of XPO1 as a critical factor involved in cell proliferation and growth transformation of cell lines derived from multiple types of cancer." (PMID 31088931, 2019). "We believe that Bim downregulation cooperates with or contributes to Bcl-xL/Bax interaction to make cancer cells adapt to XPO1 inhibition." (PMID 31113936, 2019). "Exportin 1(XPO1), a nuclear exporter protein, has been gaining recognition in cancer progression and treatment." (PMID 31870117, 2019). "Consistently, our analysis showed that XPO1 overexpression in HCC cancer tissues was correlated with poor pathological differentiation, advanced tumor clinical stage and a poor prognosis." (PMID 31371628, 2019). "Since XPO1 is upregulated in numerous types of cancer, we first examined XPO1 expression in KMM cells compared to MM cells." (PMID 31088931, 2019). "This provided an excellent model in translational medicine for targeting of XPO1 activity in cancer therapy with promising efficacy in recent years." (PMID 31870117, 2019). "Our analysis of clinical gastric samples showed overexpression of XPO1 in cancer cells compared to normal tissue and established relevance and rationale for targeting XPO1 in patients." (PMID 31569391, 2019). "XPO1 inhibition can inhibit several critical pathways that promote cancer progression and therapy resistance, and became a potential therapeutic strategy." (PMID 31052304, 2019). "These phenomena are consistent with other reports showing that miR-30 inhibits cancer cell proliferation and that the inhibition of XPO1 suppresses tumor growth." (PMID 31382411, 2019). "Taken the data together, we have identified novel growth-promoting and growth-suppressive genes of primary and cancer cells and have demonstrated that XPO1 is a vulnerable target of cancer cells." (PMID 31088931, 2019).
cancer (continued). "The goal of this study was to examine the effects of selinexor, an inhibitor of exportin-1 mediated nuclear export, on DNA damage repair and to evaluate the cytotoxic effects of selinexor in combination with DNA damaging agents (DDAs) in cancer cells." (PMID 30112106, 2018). "In cancers, including MM, XPO1 is frequently overexpressed, leading to the enhanced nuclear export of TSPs." (PMID 29876006, 2018). "XPO1 is a new target in cancer therapy based on the development of several XPO1 inhibitors only targeting tumour cells but not normal hematopoietic cells." (PMID 30266952, 2018). "Overexpression of XPO1 allows cancer cells to evade genome surveillance and cell cycle regulation because nuclear localization is critical for the function of many TSPs." (PMID 29876006, 2018). "Since single treatment approaches are prone to fall short of expectations with regards to durability of their anti-cancer effects, we tested XPO1 inhibition in the context of a novel combination therapy, involving BH3-mimetics." (PMID 30337641, 2018). "XPO1 is the exporter of several important genome surveillance proteins and tumor suppressors and some of these proteins play a prominent role in cancer suppression." (PMID 29735942, 2018). "Inhibitors against KPNB1 and Exportin-1, a nuclear export factor of the karyopherin superfamily, have been tested in different cancers in clinical trials." (PMID 29580221, 2018). "Small molecule inhibitors of XPO1 can block this export, retaining very important and functional TSPs in the nucleus and leading to the effective killing of the cancer cells." (PMID 29735942, 2018). "Nuclear export blockade through XPO1 inhibition is a target for therapeutic inhibition in many cancers." (PMID 30115935, 2018). "In mice, XPO1 occupancy saturation at ∼10 mg/kg (∼50 mg flat dose in humans) is consistent a dose that shows anti-cancer activity in patients with heavily pretreated hematologic and solid tumors." (PMID 29299164, 2017). "PBMCs have been shown to express XPO1 at very low levels, whereas relevant cancer cell lines express the target at concentrations that allow FCCS analysis." (PMID 29299164, 2017). "Cancer cell lines and patient samples from pancreatic, lung, breast, and other cancers have been shown to have an elevated level of XPO1 protein or mRNA and correlate with poor prognosis." (PMID 29137251, 2017). "Many recent publications highlight the large role of the pivotal eukaryotic nuclear export protein exportin-1 (XPO1) in the oncogenesis of several malignancies, and there is emerging evidence that XPO1 inhibition is a key target against cancer." (PMID 28196522, 2017). "While the RP2D was being identified empirically, an in vitro assay was developed to measure the amount of XPO1 occupied by selinexor in cancer cells to inform patient selection and dosing for selinexor therapy." (PMID 29299164, 2017). "Many of these have been linked to the elusive molecular network in TNBC, providing a rationale for exploring XPO1 inhibition as a potential target for cancer therapy." (PMID 28810913, 2017). "Cell cycle effects and apoptosis occur in many different cancer-derived cell lines and xenograft models with SINE, indicating potential broad efficacy of XPO1 as an anti-cancer target." (PMID 28467801, 2017). "Aberrant XPO1 expression leads to increased nuclear export of TSPs away from their targets and perpetuation of the cancer phenotype." (PMID 29137251, 2017). "One consequence of XPO1 overexpression in cancer cells is excessive nuclear export of IκB-α to the cytoplasm where it is inactivated by proteasome-mediated degradation." (PMID 27713151, 2016).